ITGA5 (integrin subunit alpha 5)
Diseases named in the same sentence as ITGA5 in open-access papers (continued):
Sharing a sentence is not in itself a finding about the gene and the disease.
adenocarcinoma (4 papers, 2013 to 2023). A common cancer characterized by the presence of malignant glandular cells. "ITGA5 was over-expressed in histological mucinous type compared with adenocarcinomas (1.25-fold regulation; P = 0.029), and under-expressed in patients aged over 60 years, compared with those under 60 (1.54-fold regulation; P = 0.016)." (PMID 23705994, 2013). "In addition, ITGAV was significantly over-expressed in tumors showing perineural invasion (P < 0.05), and ITGA5 and ITGA6 were significantly over-expressed in mucinous-type tumors compared with adenocarcinoma (P < 0.05)." (PMID 23705994, 2013).
ITGA5 also shares sentences with these, for which no sentence is quoted: myeloma (5 papers); lung adenocarcinoma (4); lymph node metastasis (3); liver disease (2); myelodysplastic syndrome (2); pancreatic ductal adenocarcinoma (2); renal carcinoma (2); sarcoidosis (2); Sepsis (2); acute myeloid leukemia (1); astrocytoma (1); basal cell carcinoma (1); breast adenocarcinoma (1); cancers of the oral cavity (1); cancers of the oropharynx (1); cardiac disease (1); cardiomyopathy (1); Cerebral ischemia (1); cervical squamous cell carcinoma (1); Cirrhosis (1); cirrhosis of the liver (1); colorectal tumor (1); Encephalopathy (1); epidermolysis bullosa (1); esophageal squamous cell carcinoma (1); Ewing sarcoma (1); glucose metabolism disorder (1); gout (1); hematologic malignancies (1); hematological cancers (1).
A further 24 diseases each share a sentence with ITGA5 in 1 paper.